OR5H14 (olfactory receptor family 5 subfamily H member 14)
Description:
Odorant receptor.
Tractability: Antibody: UniProt places it where antibodies can reach, with medium confidence; UniProt predicts a signal peptide or a membrane-spanning region; its Gene Ontology location is reachable by antibodies, with medium confidence.
Gene: Protein-coding gene on chromosome 3 (98,147,479 to 98,156,614, forward strand). Ensembl gene ENSG00000236032.
Subcellular location: Cell membrane
Pathways (Reactome):
Sensory Perception: Expression and translocation of olfactory receptors
Gene Ontology:
Molecular function: odorant binding; olfactory receptor activity; G protein-coupled receptor activity
Biological process: sensory perception of smell; detection of chemical stimulus involved in sensory perception of smell; G protein-coupled receptor signaling pathway
Cellular component: plasma membrane; membrane
Genetic constraint (gnomAD): Missense variants: 383 observed, 342.73 expected, observed/expected ratio (o/e) 1.12, 90% interval 1.03 to 1.22. Synonymous variants: 150 observed, 121.1 expected, observed/expected ratio (o/e) 1.24, 90% interval 1.08 to 1.42.
Homologues: Orthologues: macaque OR5H14 (90% identical), dog OR5H13 (76% identical), dog OR5H16 (75% identical), mouse Or5h26 (74% identical), mouse Or5h17 (74% identical), rat Or5h17 (74% identical), rat Or5h17b (74% identical), dog OR5H12 (74% identical), dog OR5H9 (74% identical), rat Or5h26 (74% identical), mouse Or5h19 (73% identical), rat Or5h17c (73% identical), and 13 more. Paralogues in human: OR5H1 (87% identical), OR5H6 (86% identical), OR5H15 (86% identical), OR5H2 (78% identical), OR5H8 (67% identical), OR5AC2 (60% identical), OR5K1 (52% identical), OR5K4 (51% identical), OR5K2 (50% identical), OR5K3 (49% identical), OR8U1 (48% identical), OR5B12 (47% identical), and 84 more.
Diseases named in the same sentence as OR5H14 in open-access papers:
OR5H14 is named in the same sentence as 2 diseases in open-access papers, as found by Europe PMC text mining. Sharing a sentence is not in itself a finding about the gene and the disease.
OR5H14 shares sentences with these, for which no sentence is quoted: prostate carcinoma (1 paper); tumor (1).